MIR1275 (microRNA 1275)
Synonyms: hsa-mir-1275; MIRN1275; mir-1275
Gene: MicroRNA gene on chromosome 6 (33,999,972 to 34,000,051, reverse strand). Ensembl gene ENSG00000221697.
Gene Ontology:
Biological process: miRNA-mediated post-transcriptional gene silencing
Cellular component: RISC complex
Homologues: Orthologues: chimpanzee ptr-mir-1275 (100% identical).